LINC00921 (long independently transcribed non-coding RNA 921)
Synonyms: FLJ39639
Gene: Long non-coding RNA gene on chromosome 16 (3,263,743 to 3,269,151, forward strand). Ensembl gene ENSG00000281005.
Diseases named in the same sentence as LINC00921 in open-access papers:
LINC00921 is named in the same sentence as 3 diseases in open-access papers, as found by Europe PMC text mining. Sharing a sentence is not in itself a finding about the gene and the disease. The quoted sentences say what the papers report.
renal carcinoma (1 paper, 2024). A carcinoma arising from the epithelium of the renal parenchyma or the renal pelvis. "The TCGA database analysis revealed the differential expression of 7 DElncRNAs namely GAS6-AS1, MIAT, LINC00921, MMP25-AS1, C22orf34, MIR34AHG, and MIR4435-2HG in 4 distinct pathological subtypes of renal cancer." (PMID 39213211, 2024).
tumor (1 paper, 2022). "In conclusion, we confirmed the low expression status and tumor-suppressing function of linc00921 in TNBC." (PMID 35179718, 2022). "To confirm the tumor-suppressing effects of linc00921, we overexpressed linc00921 in TNBC cells by establishing plasmids." (PMID 35179718, 2022). "Taken together, these results provide evidence that linc00921 is a tumor-suppressor in TNBC." (PMID 35179718, 2022). "Finally, we established a xenograft tumor mouse model to investigate whether linc00921 acted as a tumor-suppressor in vivo." (PMID 35179718, 2022). "The results showed that low expression of linc00921 was significantly correlated with high TNM stage, large tumor size and positive lymph node metastasis but not with the age of the TNBC patients." (PMID 35179718, 2022).
LINC00921 also shares sentences with these, for which no sentence is quoted: triple-negative breast carcinoma (1 paper).